EGFR (epidermal growth factor receptor)
Diseases named in the same sentence as EGFR in open-access papers (continued):
Sharing a sentence is not in itself a finding about the gene and the disease.
tumor (continued). "Analyzing all 73 lesions (> 4.2 mL) from 26 patients showed that the geometric mean SUVpeak per patient increased by 4% (95%CI −2 to 11%; P = 0.17) per doubling in (EGFR + 1) score, assuming identical EGFR expression in all tumor lesions per patient." (PMID 31705176, 2020). "In the present study, we demonstrate that EGF released from residual tumors induces the activation of EGFR in vascular endothelial cells and stimulates vessel formation, eventually leading to angiogenesis and tumor relapse." (PMID 32630838, 2020). "Previous studies showed that upregulation of the Bcl-2 family member, myeloid cell leukemia sequence 1 (Mcl-1), is involved in EGFR signaling-mediated tumor cell survival." (PMID 32081857, 2020). "While treatment of PDX models with the MEK inhibitor pimasertib alone only slightly reduced tumor growth, treatment with the EGFR inhibitor cetuximab effectively reduced cancer proliferation by more than 70%." (PMID 31910904, 2020). "Surprisingly, an increase in Ki67 expressing tumor cells were observed in spheroids treated with cisplatin for 3 days, correlating with increased expression of EGFR." (PMID 33353547, 2020). "mRNA expression of the two basal-type markers KRT6A and KRT14 as well as EGFR confirmed comparable levels between the original tumor tissue and p-SCC." (PMID 32978523, 2020). "Previous studies identified high EGFR expression promote tumor progression, and high ERRFI1 expression can slow tumor progression." (PMID 32984316, 2020). "Conversely, patients with EGFR mutations where characterized by lower CD3 T lymphocytes infiltrating and surrounding tumor cells, while mutations in the ATM gene were associated with the high immune risk profile." (PMID 32646072, 2020). "We used this information to determine the correlation between the expression levels of EGFR with Cetuximab efficacy (expressed by the percentage of tumor growth inhibition (dt/dc)%)." (PMID 31936310, 2020). "Re-activation can result partly from improving antigen presentation by APCs, upregulation of HLA-I on tumor cells, and alleviating T cells’ inhibition after treatments such as radiotherapy, anti-EGFR mAbs/molecular agents, and anti-PD-1 immunotherapy." (PMID 33329567, 2020). "For the male population, the presence of CA9 SNP rs2071676 AG + GG genotype was also correlated to a lower tumor stage (p = 0.037) and fewer lymph node invasion (p = 0.003) in those with EGFR wild type." (PMID 32365566, 2020). "QRH-882260 is an orally bioavailable heptapeptide imaging agent labeled with the fluorophore cyanine 5.5 (Cy5.5) linked to the 7 aa peptide that binds specifically to the epidermal growth factor receptor, EGFR, and is used to image EGFR-expressing tumor cells." (PMID 33352795, 2020). "In the first blood draw taken before the beginning of any systemic treatment, an EGFR p.E746_A750del was found in both tumor tissue and in the MassARRAY analysis." (PMID 33105541, 2020). "In several researches, PTPN12 is characterized as a tumor suppressor which antagonizes EGFR/HER2 signaling, which is contrary to our findings." (PMID 32536826, 2020). "PDGFRβ leads to transactivation of EGFR via the formation of a PDGFRβ/EGFR complex, and imatinib treatment inhibits PDGFRβ-mediated cell proliferation and tumor growth in CC cells." (PMID 32708604, 2020). "In particular, Tsg101 has been demonstrated to recruit and transfer epidermal growth factor receptor (EGFR) from recycling endosomes to the plasma membrane in tumor cells." (PMID 32839388, 2020). "The significance of these findings is that they demonstrate that triple-receptor targeting using TR-PINs does provide more complete photodestruction of heterogeneous tumor nodules, which would otherwise partially evade single-receptor EGFR-targeted PDT." (PMID 32726945, 2020).
tumor (continued). "This review will discuss the role of EVs delivering EGFR or EGFR ligands either to or from tumour cells and how this can promote metastases, pre-metastatic niche formation, osteoclastogenesis, angiogenesis and immune modulation in cancer." (PMID 33143170, 2020). "Although clinically circulating ctDNA detection of EGFR mutation status has been recommended by the NCCN and Chinese Society of Clinical Oncology (CSCO) guidelines as complementary means to obtain tumor tissue." (PMID 31691525, 2020). "During tumorigenesis, both immune and EGFR-mutant tumor cells are subjected to the immunoediting process consisting of dynamic and interconnected phases, including elimination, equilibrium, and finally immune evasion." (PMID 32760402, 2020). "In this study, the five anti-EGFR sdAbs inhibited cancer cell proliferation in vitro and tumor growth in vivo." (PMID 33023595, 2020). "We demonstrated that a range of drug-conjugated mAb806 ADCs targeting a tumor-specific epitope of EGFR had significant efficacy in MM models." (PMID 33023139, 2020). "miR-21 activates the EGFR/AKT signaling pathway via targeting tumor suppressor genes such as PTEN, PDCD4, APAF1, TPM1, TIMP3, RECK, FOXO1 and SPRY240." (PMID 32019988, 2020). "Here, we report results of large-scale screens combining UAS-RNAi transgenes with EGFR or Yki expression to identify negative regulators of these growth regulatory networks that can lead to aggressive tumor formation in vivo." (PMID 32737065, 2020). "EGF-like signaling ligands are also released by MMP14-mediated degradation of the laminin 5 γ2 chain to generate EGF-like fragments that drive EGFR signaling toward increased NSCLC tumor growth." (PMID 33014869, 2020). "Nevertheless, the existing genetic engineering techniques have allowed the creation of FcαRI transgenic mouse models, which have been used to confirm the powerful capacity of IgA-mediated tumor killing by myeloid cells in a few studies for EGFR+ tumors." (PMID 32983165, 2020). "Sodium/glucose co-transporter 1 (SGLT1) is essential for maintaining intracellular glucose concentration and can promote tumor growth by interacting with the epidermal growth factor receptor (EGFR)." (PMID 32806533, 2020). "The level of EGFR protein expression at the tumor cell membrane was evaluated semiquantitatively using the H-score system (HS)." (PMID 32155907, 2020). "Knockout of EGFR or/and HER-1 can impair the exosomes-mediated MAPK cell survival signaling in “tumor-associated monocytes” as they promote cancer cell survival." (PMID 32957534, 2020). "Samples for genetic testing before first EGFR-TKI treatment were mostly tumor tissues (43/49, 87.8%); while, samples used for pre-osimertinib and after osimertinib resistance testing were both mostly plasma (34/49, 69.4%)." (PMID 32385709, 2020). "Consistently, we show that PP2A‐B56 binding to ADAM17 reduces EGFR Tyr1068 autophosphorylation and suppresses in vivo tumor growth." (PMID 32400009, 2020). "Expression of AXL in the cell cytoplasm of pre-EGFR-TKI-treated tumor samples was evaluated using immunohistochemistry (IHC) staining and scored as high (3+), intermediate (2+), low (1+), and no expression of AXL." (PMID 30651547, 2019). "From a mechanistic standpoint, enhanced tyrosine kinase activity of EGFR results in Ca2+-dependent regulation of Cdc42 small GTPase activity in tumor cells, which in turn leads to phosphorylation of MLC2." (PMID 31067787, 2019). "Cytotoxicity of EGFRvIII-targeted NK-92 was restricted to EGFRvIII-positive GB cells, while dual-specific NK cells were active against tumor cells positive for EGFR and/or EGFRvIII." (PMID 31798595, 2019). "Tumor tissue and plasma specimens were collected from 25 EGFR‐mutated NSCLC patients before EGFR‐TKI treatment or after treatment failure." (PMID 31419057, 2019). "The regulation of tumor cells is assumed to depend solely on the EGFR/ERK, p38, and Fas signaling pathways." (PMID 31157216, 2019).
tumor (continued). "Recently, therapeutic mAbs targeting EGFR have been radiolabeled with multiple radioisotopes to provide information about tumor targeting, pharmacokinetics, and accumulation in critical normal organs." (PMID 30213849, 2019). "In this study, we evaluated the effect of DS-1205b, a novel, specific, small-molecule inhibitor of AXL kinase, on tumor growth and resistance to EGFR TKIs." (PMID 31497246, 2019). "CAPE can inhibit tumor cell migration and angiogenesis by efficiently blocking the EGFR signaling pathway in vitro and in vivo." (PMID 31214503, 2019). "EGFR levels in organoids were found to recapitulate EGFR expression levels of both tumor and normal patient material samples, even when retained in culture." (PMID 31694307, 2019). "Many carcinoma types, including colon, breast, and lung, display heightened EGFR activity, which correlates with tumor recurrence and shorter patient survival." (PMID 31736743, 2019). "We further demonstrated the combining YD, an AXL degrader, and EGFR-TKI resulted in overcoming resistance in EGFR-TKIs resistant NSCLC cells also delaying the emergence of resistance in EGFR-TKI sensitive NSCLC cells using tumor xenograft, and PDX model." (PMID 31043587, 2019). "AXL expression was detected in three of 12 (25%) and nine of 19 (47%) tumor specimens obtained before and after EGFR‐TKI treatment, respectively." (PMID 31419057, 2019). "The in vivo anti-tumor effect was associated with increased apoptosis and combined inhibition of the STAT3 and EGFR pathways in tumor remnants." (PMID 30674340, 2019). "The phosphorylation of NR2B by EGFR increases the intracellular Ca2+ concentration and, therefore, tumor growth and spreading." (PMID 30978987, 2019). "EGFR analysis in cfDNA is a potential alternative method for those patients who cannot obtain sufficient tumor tissue sample." (PMID 31413754, 2019). "IL-22-induced changes in the tumor microenvironment complicate EGFR-TKI acquired resistance, posing challenges for the clinical application of molecular targeted therapies." (PMID 31750252, 2019). "Of note, in this model, early lumen-filling lesions exhibited hyperactive EGFR signaling with EGFR inhibition halting tumor cell proliferation." (PMID 30961610, 2019). "EGFR is expressed at high levels in cancer cells, and its activation EGFR appears to be important for tumor progression and growth." (PMID 31406500, 2019). "This study indicated that ERs were likely to promote NSCLC progression by modulating the integrated membrane receptor signaling network composed of EGFR, Notch1 and GSK3β/β-Catenin pathways and then affecting tumor cell behaviors." (PMID 31511014, 2019). "IF and Oil Red O staining were also performed on these tumor masses, and combination treatment with the two agents significantly suppressed p-EGFR expression and LD accumulation." (PMID 30876460, 2019). "Consistent with that, miR-21 overexpression was detected in the tumor tissue of NSCLC patients that became resistant to EGFR-TKIs and correlated with poor response and shorter OS after this therapy." (PMID 31266248, 2019). "Considering that apigenin can inhibit the activation of AKT, ERK or STAT3, the major downstream signaling pathways of EGFR, we first analyzed the antitumor effects of apigenin on EGFRm tumor cells." (PMID 31367332, 2019). "Epidermal growth factor receptor (EGFR) autocrine pathway coordinates several activities relevant for tumor development and progression, including cell growth, angiogenesis, apoptosis, and metastasis." (PMID 31370258, 2019). "The use of IFN-β fusions to overcome resistance of anti-EGFR antibody by revitalizing innate and adaptive immune cells inside the tumor has also been proposed." (PMID 31393905, 2019).
tumor (continued). "An example hereof is the development of so-called bispecific light T cell engagers (LiTEs) in which scFvs targeting the CD3 molecule on T cells are coupled to nanobodies targeting EGFR tumor on cancer cells." (PMID 31695800, 2019). "Despite these efforts, EGFR-TKI single treatment has performed poorly in clinical trials for TNBC patients with advanced or metastatic breast cancer, despite clear inhibition of EGFR suggesting bypass inhibition of EGFR-related signalling in TNBC tumours." (PMID 31262335, 2019). "According to the authors, the role of EGFR signaling changes during tumor progression akin to, for example, TGF-β." (PMID 31443516, 2019). "While several mechanisms of acquired EGFR-TKI resistance have been uncovered by analyzing tumor specimens obtained at disease progression, the factors influencing the initial response and causing primary resistance to TKIs have been less studied." (PMID 31266248, 2019). "Here, the authors show that β-Catenin is predominantly integrated within the AJ complex during the early stages of this cancer and enhance EGFR signaling to promote tumour survival." (PMID 31015417, 2019). "The NCCN guidelines (National Comprehensive Cancer Network v3.2018) contemplate the use of CT and anti-EGFR, panitumumab or cetuximab, in first or second line therapies in mCRC patients whose primary tumor is localized to the left colon." (PMID 31500586, 2019). "EGFR activation or mutation and/or HER2/3 phosphorylation contribute to tumor progression and resistance." (PMID 31426807, 2019). "Since approximately 14% of the LUAD tumor cohort had Epidermal Growth Factor Receptor (EGFR) activation, and EGFR plays a known role in the replication of embryonic epidermal cells, it was included in the study as a LUAD proliferation factor." (PMID 31857847, 2019). "We found that HMGA2 knockdown inhibited many tumour signalling pathways, such as the EGFR, TGF-β, cell cycle, and PI3K-AKT signalling pathways." (PMID 31053152, 2019). "The discriminative power of circulating miR-504 was particularly high for a subgroup of NSCLC patients with EGFR exon 19 deletions in their tumours (AUC = 0.81; p < 0.0001)." (PMID 30953094, 2019). "Among the EGFR wild-type group, 12 patients had KRAS mutations, 2 had ALK-rearrangements and 21 patients had EGFR/KRAS/ALK wild-type tumours." (PMID 30953094, 2019). "Consistent with this concept, among our nine evaluable patients who harbored EGFR amplification by cfDNA analysis, anti-EGFR–based therapies led to tumor reduction in 66.7% (six of nine) including 55.6% (five of nine) who achieved a PR." (PMID 31058253, 2019). "Altogether, these results show that the pharmacological inhibition of the EGFR/mTOR/HIF-1 axis has an effective anti-tumor activity in a resistant model of HNSCC cell line, in vitro and in vivo." (PMID 31640284, 2019). "Because tracheal branches grow excessively in the EGFR-Pcn tumor model, we investigated if Bnl signaling is upregulated in tumor discs." (PMID 31568500, 2019). "While the anti-tumor activity of gefitinib remains to be fully characterized, it is reported to competitively bind to the intracellular ATP-binding domain of EGFR, thereby inhibiting tyrosine kinase activity." (PMID 30975211, 2019). "CONAN-1 was reported to have a serum half-life of 2-3 days and to inhibit tumor outgrowth albeit at a lower potency as the EGFR targeting antibody cetuximab (Erbitux®)." (PMID 31695800, 2019). "Ten patients (34.5%) harbored wild-type RAS in their tumor tissues, and out of them, 6 (20.7%) patients received anti-EGFR antibody therapy before blood sample collection." (PMID 31758080, 2019).
tumor (continued). "As EGFR is highly associated with tumor migration and invasion, we tested effect of FOXO1-miR-96-DUSP1 axis on EGFR signaling." (PMID 31579447, 2019). "EGFR is expressed at higher levels in TNBC tumours compared to ER-positive BC tumours; also in human basal A and basal B TNBC cell lines, there is a higher EGFR expression than in human luminal cell lines." (PMID 31262335, 2019). "Previous results have shown that EE02 inhibits the proliferation of tumor cells by targeting the JXM domain of EGFR." (PMID 31118055, 2019). "Epidermal growth factor receptor (EGFR) is a key tumour driver, and the EGFR signalling pathway has been shown to be a main target in the successful treatment of NSCLC." (PMID 31331328, 2019). "Secondly, the theranostic agent presented in this study only inhibits the EGFR pathway whereas other pathways can be involved in tumour growth." (PMID 30612556, 2019). "Copy number variation of molecular targets, as assessed in both tumour and cfDNA, has been shown to impact on therapeutic targeting of ERBB2, FGFR, and EGFR, with high level amplifications being associated with more favourable responses." (PMID 31137920, 2019). "Before starting osimertinib, a tumour tissue DNA PCR assay was performed to ascertain the EGFR genotyping." (PMID 31393074, 2019). "Repeated tumor biopsy comprehensively analyzed the drug resistance mechanism of advanced patients with EGFR-TKIs." (PMID 31346515, 2019). "In the context of epigenetic regulation by RTKs, it was also reported that EGFR acetylation plays a role in the function of the receptor, leading to tumor cell resistance to histone deacetylase inhibitors." (PMID 30621219, 2019). "DTLL was able to be immediately internalized into tumor cells guided by EGFR/HER2, whereas LDM reached the inside of the cells only after its passive endocytosis, therefore DTLL was able to function more effectively." (PMID 30681288, 2019). "Following an anti-EGFR therapy “holiday”, CRC cells are considered to repopulate, making the tumor once again sensitive to anti-EGFR treatment." (PMID 31623125, 2019). "The expression of HER2 and EGFR in both primary tumours and ovarian metastases was analysed by immunohistochemistry (IHC) in 31 CRC patients with ovarian metastases as well as in the primary tumours of 26 CRC patients with non-ovarian metastases." (PMID 30858756, 2019). "It is a next-generation IL-2 fusion protein for efficient delivery of sumIL-2 not only to target EGFR positive tumor tissue but also to target CTL in TME for resulting in more effective tumor killing." (PMID 31462678, 2019). "We propose that Kismet with Trr establishes a chromatin state that limits EGFR proliferative signaling, preventing tumor-like stem cell overgrowths." (PMID 31112698, 2019). "The treatment allowed for efficient localization of the tumor through fluorescence (using the same fluorophore in both formulations) and EGFR/VEGF detection through the use of distinct SERS labels." (PMID 31662751, 2019). "EGFR overexpression in head/neck SCC is reported and associated with tumor stages and tumor-free survival." (PMID 31831717, 2019). "First, we demonstrated that targeted IFN fusions (PD-L1 and EGFR) selectively induced IP-10 secretion from antigen positive tumor cells, which was critical in recruiting the effector T cells to the tumor microenvironment." (PMID 31393905, 2019). "For example, miR-7, a miRNA characterized as tumor suppressor for multiple cancers, regulates glioma growth and invasions via targeting EGFR, focal adhesion kinase, and IRS-1, IRS-2, and other genes, and downstream Akt pathway." (PMID 30644073, 2019). "The Kaplan- Meier analysis was supportive of the results obtained from the Cox proportional hazard model, revealing a strong inverse correlation between total tumor EGFR expression and disease-specific survival." (PMID 30630536, 2019).